DICER1 (dicer 1, ribonuclease III)
Diseases named in the same sentence as DICER1 in open-access papers (continued):
Sharing a sentence is not in itself a finding about the gene and the disease.
tumor (continued). "On the other hand, poor prognostic factors include preoperative tumor rupture as well as the presence of a poorly differentiated SLCT component, which is associated with heterozygous hotspot mutations in the RNase IIIb domain of DICER1." (PMID 41416308, 2025). "Given the development of DICER1 mutant ETMRs in very young infants, they may represent the earliest-onset tumor type under the DICER1 syndrome umbrella." (PMID 40361440, 2025). "We also found significant correlations between DICER1 gene expression and the infiltration of various immune cells and immune function scores, highlighting its potential regulatory role in the tumor microenvironment." (PMID 40666073, 2025). "Tumor sequencing identified two somatic DICER1 variants, although not present in peripheral blood, thus excluding a DICER1 syndrome." (PMID 41393674, 2025). "At present, no morphologic or molecular criteria reliably distinguish oncocytic change seen in DICER1-associated tumours from that in other entities, and we do not propose a diagnostic category of ‘DICER1-associated oncocytic morphology’." (PMID 41104964, 2025). "Additionally, DICER1 expression exhibited significant differences across various tumor stages and T stages (P < 0.05)." (PMID 40666073, 2025). "Previous studies suggest that Dicer1 acts as a haplo-insufficient tumor suppressor gene." (PMID 41002430, 2025). "Although DICER1 is usually seen as a tumor-suppressing gene, some findings suggest it could also act in ways that promote cancer, depending on the mutation." (PMID 40361440, 2025). "Given that themajority of DICER1 mutations are biallelic and inactivating inthyroid tumors and that DGCR8 mutations usually occur withconcurrent LOH, it was expected that these genetic alterations would impede themiRNA maturation process in the tumor cells." (PMID 39601261, 2024). "The genitourinary system is a hotspot of DICER-1 related neoplasms." (PMID 38254836, 2024). "The recent discovery of mutations in DICER1, STK11 and FOXL2 genes has improved our understanding in addition to the approach to sex cord stromal tumours and can serve as diagnostic and prognostic markers and may assist in risk stratification in the future." (PMID 39430077, 2024). "In addition, miR-146b-5p decreases the biosynthesis of miRNA via targeting DICER1, which is an important protein required for miRNA maturation that contributes as a tumour suppressor in TC." (PMID 39558949, 2024). "The complete understanding of the penetrance for each of the DICER1-associated neoplasms in inherited conditions is not yet established." (PMID 38254836, 2024). "Dicer1 has been suggested to be a haploinsufficient tumor suppressor gene." (PMID 39409030, 2024). "This family is registered in the IPPB registry, and this follow-up may shed additional light on type I PPB DICER1-related tumor." (PMID 36902703, 2023). "Approximately 10% of cases have no germline DICER1 pathogenic variant but have a somatic mosaic for a DICER1 tumour predisposition variant (detected in many tissues, not only in tumours)." (PMID 37626640, 2023). "DICER1 is an important gene, located on chromosome 14q32.13 in the biogenesis of microRNAs, a class of small RNA molecules essential in organ development and suppression of neoplasia." (PMID 36902703, 2023). "This suggests that DICER1 alterations may induce or contribute to distinct tumor phenotypes dependent on the specific cellular context." (PMID 36966138, 2023).
tumor (continued). "As with other suspected examples of DICER1-associated neoplasms, especially non-vaginal ERMS in the müllerian tract, appropriate molecular testing on the neoplasm should be pursued in addition to a discussion with the clinician." (PMID 34599283, 2022). "However, no second hit was found in the NB, leading to its status as a DICER1-related tumor being questioned." (PMID 36151231, 2022). "An aggressive tumor linked with DICER1 mutation, but not with DICER1 syndrome, is malignant teratoma of the thyroid gland, and the term “thyroblastoma” has been proposed for this entity." (PMID 35008368, 2021). "Currently, several studies have shown that the expression level and mode of action of Dicer1 may vary depending on the type of tumor, but the regulatory mechanism of these genes remains unclear." (PMID 33763118, 2021). "Accurate estimates of the prevalence of DICER1 mosaicism and tumor-confined variation are also crucial to providing useful clinical risk estimates and genetic counseling; this study found that the genome-first approach is effective in providing data toward determining those estimates." (PMID 33630087, 2021). "Tumor infiltration of leukocytes/lymphocytes was unaltered by host platelet miRNA deletion; however, we cannot completely rule out potential direct or indirect effects of Pf4-Cre-mediated Dicer1 deletion in blood cells in addition to platelets." (PMID 34936674, 2021). "Firstly, approximately 95% of non-index case individuals with germline pathogenic DICER1 variants did not develop a tumor by age 10 years." (PMID 34170462, 2021). "Dicer1, an RNase, has been considered as a tumor regulator in many tumors." (PMID 33763118, 2021). "Interestingly, Dicer1 downregulation was statistically correlated with tumor progression, tumor grade, and lymph node metastasis." (PMID 33763118, 2021). "Metformin also acts in a DICER1‐dependent manner and applies its anti-tumor effects." (PMID 33849540, 2021). "Interestingly, in one other tumor both the TERT C228T variant and two DICER1 variants were found (E1813D and a stop-gain variant Q1230 * predicted to result in nonsense-mediated decay)." (PMID 32455687, 2020). "DICER1 contains two CpG islands in its promoter region and is an RNaseIII endonuclease that plays an important role in the process of processing pre‐miRNA into active mature miRNA and correlated with various tumours." (PMID 33085184, 2020). "The age of onset (29 to 65 years) and negative family history suggested that the DICER1 variants identified were somatic in nature and they stay in sharp contrast to those inherited DICER1-related neoplasms." (PMID 32507920, 2020). "The single tumor lacking the C19MC amplification displayed a DICER1 mutation and clustered with other ETMRs (C19MC altered or NOS)." (PMID 33392079, 2020). "Nonetheless, the penetrance of each of the DICER1-associated neoplasms in inherited conditions is not fully understood." (PMID 33552988, 2020). "In addition, the two miR-103/107 and miR-191/425 clusters targeting the DICER1 gene influenced BC miRNA processing deregulation, and their up-regulation promoted BC tumor cell growth, invasion, and metastasis." (PMID 31683635, 2019). "To examine the effects of DICER1 on tumor-specific phenotpyes in vitro, we performed loss-of-function and gain-of-function studies using the cell lines Cal62 and TPC1, which have intermediate levels of DICER1, and with SW1736, which has low levels of DICER1." (PMID 30967628, 2019). "Moreover, LINC00899 was found to competitively bind miR-425, thereby functioning as a tumor suppressor by enhancing DICER1." (PMID 31739288, 2019).
tumor (continued). "Similarly, miR-192 has been reported as an independent prognostic marker for relapse in NB patients; miR-192 directly targets Dicer1 and was functionally designated as a tumor suppressor miR." (PMID 31867575, 2019). "Another study indicated that fluoxetine, a serotonin reuptake inhibitor, upregulated miR-572 and miR-663a consistently in NB cells and thereby inhibited their crucial targets (mir-572 - Cdkn1, Dicer1, Wnt7a; miR-663a - TGFβ1, PTEN, VEGFA) associated with NB cell differentiation and tumor evolution." (PMID 31867575, 2019). "Therefore, DICER1 is one of the most important components involved in miRNA biogenesis and its expression level seemed to correlate with tumor initiation, progression and patients’ prognosis." (PMID 29976158, 2018). "Furthermore, knockdown of Dicer1 in HC-MSCs promoted cellular senescence and tumor-supporting capacities, while decreasing the differentiation of MSCs." (PMID 29724992, 2018). "The main possible drivers for this neoplasia were DICER1, NF1 and MYC." (PMID 29459759, 2018). "Dicer1 knockdown increased the tumor-supporting properties of MSCs." (PMID 29724992, 2018). "DICER1 (SSC7), associated with ulceration is a key player of miRNA synthesis and responsible for the DICER1 syndrome, a condition that increases the risk of developing various types of tumours in families of patients." (PMID 29963229, 2018). "MiR-107 was found to target DICER1 and thereby regulate tumor invasion and metastasis." (PMID 28589857, 2017). "Macrophage‐specific Dicer1 deletion significantly delayed tumor progression." (PMID 29024380, 2017). "Additionally, rs417309 of DGCR8, rs3742330 and rs13078 of DICER1, and rs784567 of TARBP2 as well as rs11077 of XPO5 are associated with the progression of LC depending on the tumor size and lymph node metastases." (PMID 26688807, 2015). "In addition, the rs3742330 of DICER1, rs784567 of TARBP2, rs417309 of DGCR8, and rs14035 of RAN as well as rs11077 of XPO5 are associated with the LC progression depending on the tumor size." (PMID 26688807, 2015). "Micro-RNAs (miRNAs) are critical for tumor suppression, which is most notably revealed following genetic manipulation of Dicer1, an enzyme needed for miRNA processing, in which haplo-insufficiency of Dicer1 and global reduction of miRNA levels significantly accelerates tumorigenesis." (PMID 26244988, 2015). "Considering all these data, one can further speculate that DICER1 can function both as a tumor suppressor and an oncogene." (PMID 25883138, 2015). "In light of the newly established link between NCMH and DICER1 mutations surgeons should be vigilant for associated DICER1 tumours, as NCMH may be the ‘herald tumour’ of this disease spectrum." (PMID 26138824, 2015). "DICER1 is not a classical tumor suppressor gene for which “two hits” – loss of function in both alleles – are required to allow tumorigenesis." (PMID 26925222, 2015). "Surgeons and physicians should therefore either offer DICER1 mutation analysis if available, or ensure long-term follow up of these patients and be vigilant for associated tumours, as NCMH may be the ‘herald tumour’ of this disease spectrum." (PMID 26138824, 2015). "In addition, the downregulation of DICER1 has been associated with the miR-200 family-EMT pathway and tumor metastasis, which indicates poorer prognosis." (PMID 23680357, 2013). "Loss of a single Dicer1 allele does not appear sufficient to induce cancer, despite its ability to reduce time to tumor onset and overall survival murine models of cancer." (PMID 23641362, 2013). "Dicer1 may be important in NB tumor initiation, since NB is a childhood cancer arising from the sympaticoadrenal lineage of the neural crest." (PMID 24223844, 2013).
tumor (continued). "In contrast, Ravi and colleagues recently showed that full loss of Dicer1 did not preclude tumor formation." (PMID 23222681, 2012). "In addition, Dicer1-null cells from a sarcoma cell line, though depleted of miRNAs, were competent for tumor formation." (PMID 23222681, 2012). "As we found many changes in miRNA expression across the five clinical tumor subtypes we had defined above, we asked whether DICER1, DROSHA, DGCR8, AGO1, AGO2, AGO3 or AGO4 expression differs among these subgroups." (PMID 17922911, 2007). "Inherited alterations in the DICER1 gene can cause an autosomal dominant genetic susceptibility to several tumour types, especially childhood‐onset pleuropulmonary blastoma (PPB) and other tumours including those of the kidney, thyroid, ovary, cervix, brain and eye." (PMID 40689426, 2025). "In addition to the constitutional DICER1 p.(Tyr1357fs*18) variant, the somatic DICER1 p.(Asp1910Tyr) oncogenic variant and the somatic CTNNB1 p.(Thr41Ala) oncogenic variant were also identified in this tumor." (PMID 40892116, 2025). "Moreover, the expression level of DICER1 affects the sensitivity to multiple drugs and may influence the tumor microenvironment through the modulation of intercellular communication." (PMID 40666073, 2025). "Additionally, somatic DICER1 mutations can result in comparable tumour manifestations in patients lacking germline mutations." (PMID 40007992, 2025). "In addition to the constitutional and somatic DICER1 oncogenic variants, the somatic CTNNB1 p.(Thr41Ala) oncogenic variant was also identified in the present tumor, which also justified its histopathogenic relationship with the family of tumors containing CD10-positive morulae." (PMID 40892116, 2025). "Additionally, as more DICER1 variants are curated, the VCEP can revisit the odds of pathogenicity calculations for various evidence codes such as PP4 tumor phenotype evidence or PP3 and BP4 in silico predictor cutoffs and modify the strength of the evidence codes as appropriate." (PMID 38084291, 2023). "We would concur that any combination of these patterns or a predominance of one of these patterns should raise the possibility of a DICER1-associated neoplasm to initiate appropriate molecular testing, regardless of the site of presentation in a child or adolescent." (PMID 34599283, 2022). "Both cases confirm previous findings on intracranial RMS-like tumors with DICER1 mutation typically carrying genetic characteristics unequivocally detectable by DNA methylation analysis and NGS while the histomorphology is highly diverse and tumor cells appear heterogeneous." (PMID 36380356, 2022). "The term DICER1 did not appear in any of the medical records of the 25 participants with a pLOF DICER1 variant, even in those affected with a known DICER1-associated tumor or thyroid phenotype." (PMID 33630087, 2021). "Moreover, DICER1 is not a classical tumor suppressor gene for which “two hits”—loss of function in both alleles—are required to allow tumorigenesis." (PMID 33922805, 2021). "Metformin may also act in a DICER1‐dependent manner and apply its tumor suppressing effects." (PMID 33849540, 2021). "In addition, exosomes transferring miRNA-107 from tumor expand and activate myeloid-derived suppression cells to promote immunosuppression in the tumor microenvironment and help GC cells’ growth and survival by targeting DICER1 and PTEN gene." (PMID 34268118, 2021). "In 21 patients, DICER1 mutations were identified in the tumor, but germline DNA was not analyzed." (PMID 33673661, 2021). "Genomic sequencing of the tumor was negative for a DICER1 mutation." (PMID 33196040, 2020).
tumor (continued). "The finding that miR-146b overexpression induces a global downregulation of miRNAs, including important tumor suppressor miRNAs such as miR-30a-5p, miR-30a-3p, miR-100, and miR-204, suggests that the aggressiveness traits induced by this miRNA are likely elicited by DICER1 inhibition." (PMID 30967628, 2019). "The let-7 family has previously been suggested as a tumor suppressor miRNA family that could be compromised by DICER1 RNase IIIb cancer hotspot mutations, but clear linkage to endogenous DICER1 tumor signature has not been established." (PMID 31417090, 2019). "Previous studies reported that DICER1 and miR-375 were positively correlated, and DICER1 might be involved in the feedback regulation of miR-375, which has been recognized as an important tumor suppressor." (PMID 29853562, 2018). "Furthermore, the DGCR8 rs1640299, DICER1 rs3742330 and rs13078, RAN rs14035, and XPO5 rs11077 as well as rs784567 of TARBP2 genes single nucleotide polymorphisms have demonstrated an association with tumor progression depending on the lymph node metastases." (PMID 26688807, 2015). "There are also many controversies whether DICER1 acts as a tumour suppressor or an oncogene." (PMID 25883138, 2015). "Therefore, clinical follow-up studies of patients with pathogenic DICER1 mutations with and without neoplastic diseases are required for improved counseling and treatment." (PMID 24708902, 2014). "As DICER1 is involved in cleaving the precursor miRNAs into mature miRNAs, variation in DICER1 expression might result in altered turnover rates of the precursor miRNAs and, hence, higher concentrations of mature miRNAs in those tumor samples with higher DICER1 expression." (PMID 22353773, 2012). "Other protective genes, including DYRK1A, DICER1, MYOD1 and INTS6, also contribute to tumor suppression through diverse mechanisms." (PMID 40561176, 2025). "In this section, we report its observed frequency in DICER1- and DGCR8-altered tumours strictly as an observational correlate." (PMID 41104964, 2025). "Both DICER1 and DGCR8 are postulated to exhibit tumor-suppressive functions, which is supported by the biallelic inactivation pattern observed in syndromic and sporadic cases." (PMID 38252873, 2024). "To gain a more detailed insight into class-specific methylation patterns we analyzed overall methylation levels of LGMT DICER1, SARC DICER1 and PIS DICER1 in the context of other neoplasms." (PMID 36966138, 2023). "Of the neoantigens with a strong affinity, four originated from tumor related genes (ARID2, DICER1, PAX8, and PTEN)." (PMID 37932340, 2023). "We decided to focus our attention on the possible role of APE1 in the expression of DICER1 since the downregulation of DICER1 was related to EMT and tumor metastasis." (PMID 35876890, 2022). "Focally deleted regions identified the tumour-suppressor genes RHOA at 3p21, CDKN2A and CDKN2B at 9p21, RAD51B, MAX, DICER1, BCL11B, NKX2-1, CCNB1IP1 and BAZ1A at 9q33." (PMID 34980126, 2022). "Only one tumor, previously diagnosed as ERMS arising in the maxilla of a 6-year-old boy clustered with DICER1-mut ERMS of the uterus." (PMID 33846547, 2021). "GC-derived exosomes carrying miR-107 are able to promote MDSC expansion and activation via targeting DICER1 and PTEN, therefore suppressing tumor growth and augmenting immunotherapy efficacy." (PMID 34805143, 2021). "To conclude, we show that GABPA directly regulates DICER1 in FTC, acting as a tumour suppressor and displaying down-regulation in clinical samples." (PMID 32163919, 2020). "We observed significant over-expression of ADAR, ADARB1, DDX5/17/20, DGCR8, DICER1, DROSHA, EIF2C1-4 (AGO1-4), GEMIN4, POLR2A, TARBP2, TNRC6A and XPO5 in tumor tissue compared to adjacent mucosa." (PMID 31510013, 2019). "The expression of AUF1 and Dicer1 in HCC tissues and the adjacent non-tumor tissues from 20 patients were determined by immunohistochemistry and quantitative real-time PCR (qRT-PCR)." (PMID 29599909, 2018).